ZEB1 (zinc finger E-box binding homeobox 1)
Diseases named in the same sentence as ZEB1 in open-access papers (continued):
Sharing a sentence is not in itself a finding about the gene and the disease.
prostate carcinoma (continued). "NHE-1 is usually highly expressed in prostate cancers and correlates with the expression of transcription factors, such as Zeb1, which promote the mesenchymal transition and, consequently, the invasion and metastatic potential of the tumor lesions." (PMID 36230838, 2022). "For this purpose, lncRNA IUR decreases ZEB1 expression via miRNA-200 upregulation to impair prostate cancer progression." (PMID 35773731, 2022). "In prostate cancer, ZEB1 promotes vasculogenic mimicry through Src signaling, which is associated with mesenchymal and cancer stem cell phenotypes." (PMID 35454770, 2022). "Then they found that up-regulating circZEB1 can increase the expression of ZEB1 by sponging miR-141-3p, thereby making the prostate cancer cells develop radioresistance." (PMID 36142355, 2022). "The ERK/MAPK pathway activates ZEB1 transcription to induce prostate cancer cell invasion and metastasis via hepatocyte growth factor." (PMID 35454770, 2022). "In prostate cancer, ZEB1 overexpression has become an important marker molecule for metastasis assessment." (PMID 33391437, 2021). "In this context, it has been reported that ZEB1 regulates the CSC population of prostate cancer, also characterized by CD44 expression." (PMID 34502091, 2021). "Next, we assessed the effect of Zeb1 knockdown on migration and invasion of PC-3 prostate cancer cells using transwell migration (gelatin) and physical barrier wound healing assays." (PMID 34884649, 2021). "The current work indicated that ZEB1 functions as a transcription factor of miR-142-5p, while data from another group indicated that ZEB1 is involved in PTX-resistance in prostate cancer." (PMID 34163033, 2021). "Mesenchymal human PC-3 prostate cancer cells were engineered with an inducible lentiviral shRNA system to knockdown expression of the master EMT regulator Zeb1." (PMID 34884649, 2021). "In the current manuscript we created and characterized a stable inducible p-EMT cell line model by decreasing Zeb1 expression in mesenchymal PC-3 prostate cancer cells." (PMID 34884649, 2021). "We had originally expected that knockdown of Zeb1 in mesenchymal PC-3 prostate cancer cells would lead to a mesenchymal-to-epithelial (MET) transition and reduced metastatic cell behaviors such as migration and invasion." (PMID 34884649, 2021). "A similar result has previously been reported, in that ZEB1 knockdown increased cell surface expression of β4 integrin in prostate cancer cells." (PMID 33883697, 2021). "With respect to EMT induction, the regulation of YAP1 expression by direct binding of miR-375 was controlled by ZEB1 in prostate cancer, thereby forming a feedforward cycle." (PMID 32252322, 2020). "In prostate cancer cells, ZEB1 stimulates up-regulation of ATP-binding cassette subfamily C member 10 (MRP4) to export docetaxel out of cancer cells, resulting in their decreased sensitivity to chemotherapy." (PMID 32664703, 2020). "A study about prostatic carcinoma found that miR-205-5p inhibited cell migration and invasion by targeting zinc finger E-box binding homeobox 1 expression." (PMID 32869841, 2020). "LncRNA IUR can inhibit the migration and metastasis of prostate cancer cells via enhancing the expression of miR-200, which in turn inhibits ZEB1." (PMID 32664703, 2020). "miR-373-3p is known to induce mesenchymal-epithelial transition in prostate cancer cells by inducing the expression of E-cadherin or inhibiting ZEB1 post-transcriptionally." (PMID 32231998, 2020). "For instance, ZEB1 expression is elevated in prostate cancer and inhibits cell proliferation and invasion." (PMID 31007650, 2019). "miR-205 reconstitution was able to significantly enhance the radiation response of prostate cancer cell lines and xenografts through the impairment of radiation-induced DNA damage repair, as a consequence of PKCε and ZEB1 inhibition." (PMID 30717752, 2019).
prostate carcinoma (continued). "Histones modified are important in tumorigenesis and progression in cancer; for example, H3K4me3 modification of the ZEB1 promoter region results in upregulation of ZEB1 and eventually leads to the proliferation and migration of prostate cancer cells." (PMID 30674889, 2019). "Consistent with its reciprocal relationship with miR‐200 and miR‐375 in cancer, QKI expression increased during TGF‐β‐induced EMT of human breast and canine kidney epithelial cells and during ZEB1‐induced EMT of LNCaP human prostate cancer cells." (PMID 29871889, 2018). "Prostate cancer cells were subjected to ZEB1 knockdown or overexpression and assessment of the effects on vasculogenic mimicry formation in vitro and in vivo." (PMID 29754422, 2018). "SIRT1 induces the EMT by cooperating with ZEB1; together, these components function to enhance cell migration and metastasis in prostate cancer." (PMID 29531814, 2018). "Recent study demonstrated that loss of ΔNp63 and miR‐205 enhanced cell migration and metastasis via targeting expression of ZEB1 in prostate cancer." (PMID 29150940, 2018). "Alike ZEB1 also SNAI1 and SNAI2 are strongly associated with high Gleason score 10, indicating them as markers of an aggressive and advanced prostate cancer phenotype." (PMID 29206234, 2017). "Analysis of ZEB1 immunostaining across the two patient groups identified a significant increase in ZEB1 expression in prostate cancer patients treated with docetaxel." (PMID 28133913, 2017). "Two Androgen Response Elements (AREs) in the ZEB1 promoter are both required for ZEB1 induction by androgens in an artificial promoter transfection system in prostate cancer cells." (PMID 26797644, 2016). "A ZEB1-miR-375-YAP1 pathway was recently found to regulate epithelial plasticity in prostate cancer, while ZEB1 together with STAT3 were identified as key molecules altered at the early stages of prostate carcinogenesis." (PMID 28042859, 2016). "Depletion of ZEB1 in the prostate cancer cell line DU145, which is known to form osteolytic bone metastases, again decreased the expression of NOG mRNA and protein, as well as FST." (PMID 25973542, 2015). "ZEB1 can also recruit the nicotinamide adenine dinucleotide-dependent HDAC SIRT1 in prostate cancer cells to repress E-cadherin and to induce several EMT markers." (PMID 24216980, 2013). "Nonetheless, these data confirm our data in 22RV1 prostate cancer cells that endogenous ZEB1 mRNA levels are increased by androgen." (PMID 22190929, 2011). "The ZEB1/deltaEF1 and ZEB2/SIP1 transcriptional suppressors of E-cadherin and the miR-200 family are components of a signaling network, and the latter has been found to regulate PDGF-D-linked EMT in prostate cancer cells." (PMID 40801639, 2025). "The transcription factor zinc finger E-box binding homeobox 1 (ZEB1) has been identified as a key transcriptional regulator of EMT in prostate cancer, with its aberrant expression occurring partly in response to Insulin-like growth factor-I (IGF-I) IGF-I stimulation." (PMID 39459070, 2024). "Interestingly, the inducible knock-down of ZEB1 resulted in a partial EMT phenotype in PC-3 prostate cancer cells including co-expression of epithelial and mesenchymal markers, a mixed E/M morphology and an increased invasion and migration capacity." (PMID 38139138, 2023). "Conversely, in prostate cancer, SIRT1 causes an increase in cell migration and metastasis, physically interacting with the zinc finger transcription factor ZEB1, thus suppressing E-cadherin transcription through histone H3 deacetylation in the E-cadherin proximal promoter." (PMID 35745656, 2022). "The ZEB1 is also involved in prostate cancer and transcriptional misregulation in cancer." (PMID 35098570, 2022). "Taken together, they concluded that radiation-induced TR4 expression affects the radiosensitivity of prostate cancer through the QKI/circZEB1/miR-141-3p/ZEB1 axis, making prostate cancer radioresistant, and targeting TR4 therapy may be a solution." (PMID 36142355, 2022).
prostate carcinoma (continued). "Furthermore, overexpression of ZEB1 promotes growth and metastasis as well as induces drug resistance in prostate cancer." (PMID 35773731, 2022). "In breast cancer cells, it has been demonstrated that Notch can directly induce Slug, but not Snail and Twist1, while in prostate cancer, Notch was associated with Snail and Zeb1." (PMID 35745656, 2022). "Expression of NHE1 in DU 145 prostate cancer cells correlates with Zeb1 expression." (PMID 34948058, 2021). "We have shown that Enza, a new generation hormone therapy, promotes prostate cancer cells neurodifferentiation by activating a positive feedback loop between the key transcription factor of epithelial to mesenchymal transition Zeb1 and the calcium-sensitive potassium channel SK3." (PMID 34204608, 2021). "On this topic, ZEB1 was identified as a transcriptional repressor of SDC1 in prostate cancer cells." (PMID 34208075, 2021). "Following Dox induction (72 h), we observed that Zeb1 protein and RNA expression were significantly decreased compared to all ctrl cells (p ≤ 0.05), down to a level equivalent to that of human LNCaP cells, an epithelial prostate cancer cell line." (PMID 34884649, 2021). "Moreover, the core EMT-TF ZEB1 was identified as a transcriptional repressor of SDC1 in prostate cancer cells." (PMID 34208075, 2021). "Interestingly, ZEB1 was recently identified as a repressor of SDC1 in prostate cancer cell lines displaying EMT characteristics." (PMID 34208075, 2021). "In prostate cancer cells, ZEB1 plays dual functions in order to repress E-cadherin and at the same time activates Vimentin by recruiting SET8 (a histone H4K20-specific methyl transferase) to E-cadherin promoter and activate a ZEB1-dependent H4K20 monomethylation, respectively." (PMID 32549375, 2020). "For that purpose, we crossed the Zeb1/tdTomato mice with the Hi-Myc prostate cancer mouse model." (PMID 32024836, 2020). "It has been shown that up-regulation of ZEB1 drives EMT in human prostate cancer cells." (PMID 32252623, 2020). "In addition, we examined the Zeb1+ epithelial cells in two other GEMM models of prostate cancer, the Probasin-Cre; Ptenfl/fl (PKO) model and the TRAMP model." (PMID 32024836, 2020). "Besides, some studies have investigated the interaction between ZEB1 and AR in breast and prostate cancer 19–21." (PMID 32153739, 2020). "This Zeb1+ luminal cell population might represent prostate tumor initiating cells, which can be also related to two different cellular origins for prostate cancers: basal versus luminal cells." (PMID 32024836, 2020). "Moreover, siRNA-mediated silencing of ZEB1 recapitulated the effect of miR-205 re-sensitization, confirming its functional role in radiotherapy of prostate cancer." (PMID 32266287, 2020). "A recent study in small cell lung cancer identified a link between EMT and resistance to PARP inhibitors in that disease setting and PARP-1 has been shown to regulate EMT in prostate cancer models through regulation of TGFβ signalling and changes in levels of ZEB1." (PMID 31080552, 2019). "In addition, some studies also verified that high expression of ZEB1 expedited the development of drug resistance in prostate cancer and non-small-cell lung cancer." (PMID 31793989, 2019). "Furthermore, ZEB1 was required for VM formation and altered expression of EMT‐related and CSC‐associated proteins in prostate cancer cells in vitro and in vivo." (PMID 29754422, 2018). "AR is reported to be suppressed by N-Myc in NEPC and the p38MAPK/FOXC2/Zeb1 pathway in prostate cancer stem-like cells (PCSCs), and inhibition of FOXC2 can reduce stem cell properties and restore AR/PSA expression and also sensitivity to docetaxel in DU145 cells." (PMID 29555975, 2018). "Another study showed that miR-128 sensitizes prostate cancer cells to CDDP by suppressing ZEB1." (PMID 29849953, 2018).
prostate carcinoma (continued). "The data showed that the presence of VM and high ZEB1 expression was associated with higher Gleason score, TNM stage, and lymph node and distant metastases as well as with the expression of vimentin and CD133 in prostate cancer tissues." (PMID 29754422, 2018). "MiR-128 targets ZEB1 in prostate cancer, and the miR-128-ZEB1 axis could be a promising prognostic and therapeutic target for future prostate cancer therapy." (PMID 28938540, 2017). "ZEB1 is induced by AR in prostate cancer cells and in triple-negative breast cancer cells." (PMID 26797644, 2016). "Here we expand on our earlier studies and show that the mechanism of FLASH-dependent control of ZEB1 function is conserved in multiple cancer cell lines, including cervical, breast, pancreas and prostate cancer, and it is dependent on ZEB1 proteasomal degradation." (PMID 27526108, 2016). "This means that ZEB1 could function as a possible biomarker for predicting the onset of metastatic spread in prostate cancer." (PMID 24877145, 2014). "Indeed, increased H3K9 acetylation (a mark of active chromatin) and increased RNA pol II occupancy were found on the E-cadherin promoter concomitant with ZEB1 knockdown in DU145 prostate cancer cells." (PMID 24216980, 2013). "During EMT of prostate cancer cells, the expression of transcription factors such as Snail, Slug, Twist, E47, ZEB1, and ZEB2 is increased, which leads to increased expression of N-cadherin and vimentin and concomitantly decreased expression of E-cadherin and cytokeratins." (PMID 23785446, 2013). "A most recent study revealed that ZEB1 expression could enhance transendothelial migration in prostate cancer cells." (PMID 21152091, 2010). "The dysregulation of miR-409 has been detected in many neoplasms, including gastric cancer, prostate cancer, bladder cancer and lung adenocarcinoma; miR-409-3p reportedly regulates cell proliferation and invasion by targeting zinc-finger E-box-binding homeobox 1 (ZEB1)." (PMID 36769265, 2023). "Adiponectin silencing in 22RV1 cells—human prostate cancer cell—downregulates the expression of epithelial markers: E-cadherin and zonula occludens-1 (ZO-1), but upregulates the expression of mesenchymal markers: zinc finger E-box binding homeobox 1 (ZEB1), vimentin and Snail." (PMID 37686525, 2023). "Interestingly, our findings showed that down regulation of NR6A1 protein expression significantly increased E-cadherin expression, and markedly reduced N-cadherin, Vimentin and ZEB-1 expression in prostate cancer cells (DU145 and PC3), while overexpression of NR6A1 hold the opposite effects." (PMID 28969082, 2017). "Furthermore, our findings might be relevant for the osteolytic bone metastasis formation of other tumor entities as well, as we could show the regulation of NOG and FST by ZEB1 in the prostate cancer cell line DU145." (PMID 25973542, 2015). "Furthermore, treatment of prostate cancer cells with ZEB1 siRNA results in a more epithelial morphology, with increased expression of E-cadherin and decreased N-cadherin, fibronectin expression, and suppresses prostate cancer cell migration and invasion." (PMID 24618337, 2014). "TGF-β induces the EMT in prostate cancer in vitro via the suppression of E-cadherin levels, and elevates the expression of fibronectin, vimentin, and EMT-TFs such as ZEB1 and SNAI1/2." (PMID 39941895, 2025). "The results showed that the expression levels of CDH2, SNAI1, ZEB1, and ZEB2 were significantly downregulated in prostate cancer compared to controls, while the expression of CDH1 was significantly upregulated." (PMID 40693059, 2025). "Overexpression of both ZEB1 and ZEB2 has been reported in a number of cancers, including prostate cancer, breast cancer, gynecological cancers, head and neck cancers, and specifically in oral squamous cell carcinoma." (PMID 38751602, 2024).
prostate carcinoma (continued). "We evaluate the downstream effects of the Epithelial-to-Mesenchymal Transition (EMT) transcription factors, ZEB1 and SNAI1, and analyze their potential significance as biomarkers for increased aggressiveness and immune response in prostate cancer (PCa)." (PMID 38672562, 2024). "Knockdown of lnc-ZNF30-3 results in decreased migration of prostate cancer cells and downregulation of EMT drivers such as TWIST1 and ZEB1 at both the RNA and protein levels." (PMID 37434219, 2023). "In line with our findings, ZEB1 has been confirmed as a key transcriptional regulator of EMT, and its expression was elevated by IGF‐1 in prostate cancer cells." (PMID 36988055, 2023). "In prostate cancer cells, IGF-1 upregulates expression of transcriptional factor ZEB1 and also increases expression of fibronectin and N-cadherin." (PMID 36361979, 2022). "This analysis revealed a striking positive correlation between the expression of PKCα (PRKCA gene) and mesenchymal markers vimentin, ZEB1, ZEB2, and AXL in prostate cancer cell lines." (PMID 36818489, 2022). "Cell Senescence caused the differential expression of six genes belonging to the KEGG Pathway Prostate Cancer (PDGFRB, PDGFRA, CCNE2, E2F2, EGFR and ZEB1)." (PMID 35205253, 2022). "By overexpressing zinc finger enhancer-binding protein (ZEB1), ZEB1-AS1 was able to accelerate osteosarcoma and prostate cancer progression." (PMID 35992788, 2022). "Zeb1 is a transcription factor that promotes epithelial–mesenchymal transition (EMT) which is important in the progression and metastasis of prostate cancer." (PMID 34948058, 2021). "We previously identified a positive feedback loop between Zeb1 and the SK3 potassium channel that contributes to prostate cancer cell migration." (PMID 34204608, 2021). "Zeb1 is an important transcription factor that promotes epithelial–mesenchymal transition (EMT), which is important in the progression and metastasis of prostate cancer." (PMID 34948058, 2021). "For example, miR-33a-5p silencing contributed to Zinc finger E-box-binding homeobox 1 (ZEB1) upregulation, and the ZEB1 promoted epithelia-mesenchymal transition (EMT) and bone metastasis of prostate cancer." (PMID 32505219, 2020). "By targeting YAP1, miR-375 was found to inhibit prostate cancer growth, which was shown to be directly repressed by the EMT transcription factor ZEB1." (PMID 32457613, 2020). "We found that depending on age of prostate cancer patients and Gleason score EMT genes with distinctly altered expression are: KRT18, KRT19, MUC1 and COL4A1, CTNNB1, SNAI2, ZEB1 and MMP3." (PMID 29206234, 2017). "This study presents evidence for a role of ZEB1, through its transcriptional repression of E‐cadherin to be a driver of both EMT and docetaxel resistance in docetaxel‐resistant prostate cancer." (PMID 28133913, 2017). "These miRNAs were found to mediate overexpression of STAT3 and ZEB1, which are key factors in high-grade prostatic intraepithelial neoplasia (HGPIN) and initial stages of prostate cancer." (PMID 28005952, 2016). "In prostate cancer, SIRT1 enhances cell migration and metastasis by cooperating with ZEB1 to suppress E-cadherin transcription." (PMID 27528025, 2016). "Previous studies have shown that ZEB1 promoted the NOTCH ligand Jagged1 expression and activated NOTCH signalling in pancreatic and prostate cancer cells by repressing miR-200 family members, which directly targeted the 3′-UTR of Jagged1 (refs 40, 41)." (PMID 27456471, 2016). "In prostate cancer, SIRT1 was shown to enhance cell migration and metastasis by cooperating with EMT transcription factor ZEB1 to suppress E-cadherin transcription." (PMID 25424420, 2014). "E-cadherin, N-cadherin, Zeb1, Twist, Slug, Snail and other EMT markers play important roles in the regulation of the invasive and metastatic potential of prostate cancer cells." (PMID 24618337, 2014).